VDR (vitamin D receptor)
Diseases named in the same sentence as VDR in open-access papers (continued):
Sharing a sentence is not in itself a finding about the gene and the disease.
Hyperglycemia (18 papers, 2015 to 2026). An increased concentration of glucose in the blood. "One possible explanation for the increased VDR expression is a compensatory placental response to altered maternal–foetal vitamin D metabolism or hyperglycaemia-induced inflammation." (PMID 41007445, 2025). "The expression of the vitamin D receptor (VDR) in pancreatic beta cells suggests the involvement of vitamin D in insulin production, but the evidence for the association of maternal hyperglycemia with vitamin D status during pregnancy varied." (PMID 38075561, 2023). "Decrease in neurotrophins and defective calcium homeostasis increase nerve damage by toxins including hyperglycemia, also vitamin D receptor modulates neuronal cells differentiation and function." (PMID 30532515, 2018). "Studies have shown that VDR expression is significantly higher in PCs compared with ECs, and that hyperglycemia‐induced PC apoptosis can lead to the disruption of capillary homeostasis, further affecting EC survival and leading to capillary closure, thereby reducing retinal microvascular density." (PMID 41561831, 2026). "In GDM placentas, VDR protein and mRNA are 1.8-fold upregulated in extravillous trophoblasts and 5.8-fold in foetoplacental endothelial cells, potentially driven by hyperglycaemia or inflammation, though low maternal 25(OH)D concentrations may be the trigger." (PMID 41007445, 2025). "Indeed, hyperglycemia inhibited VDR expression in human vascular smooth cells, induced glycosylation of VDR in human monocytes and macrophages due to hexosamine pathway activation and interacted with VDR to impair its DNA binding and function." (PMID 30804929, 2019). "As Dex or Vitamin D receptor agonists have been described to generate tolDCs through NF-κB down-regulation, it is possible that well-controlled patients have a better capacity to overcome sustained hyperglycemia driven NF-κB activation in the process of tolDCs generation." (PMID 30804929, 2019). "One of the potential explanations for better effectiveness of DEX/VitD2-generated tolDCs from patients with tight glucose control is that hyperglycemia might attenuate the expression or function of vitamin D receptor (VDR) on monocytes used for generation of tolDCs." (PMID 30804929, 2019). "Our results provided evidence that VDR is also constitutively expressed ex vivo, in isolated rat glomeruli, and demonstrated for the first time that in our ex vivo model VDR expression and transport to the nucleus were affected by hyperglycaemia and were increased after VDRA treatment." (PMID 28664547, 2017). "Therefore, glucose‐mediated VDR increase in our ex vivo model could represent a compensatory mechanism against the hyperglycaemia‐induced inhibition of VDR binding on VDRE." (PMID 28664547, 2017). "The mechanism for vitamin D improving IR includes the following aspects: (a) Vitamin D receptor (VDR) is a key modulator of inflammation and β cell survival, whihc restored β cell function and ameliorate hyperglycemia in murine T2D models." (PMID 39014475, 2024). "Furthermore, we found that vitamin D levels were decreased in individuals with hyperglycaemia, which was not linked to either vitamin D-binding protein or Fok1 polymorphisms in the vitamin D receptor gene, although Taq1 was associated with an insufficient vitamin D status." (PMID 35956323, 2022). "These tissue-specific patterns highlight that hyperglycaemia does not uniformly increase VDR, underscoring the need for placental studies to clarify its role in GDM’s unique metabolic environment." (PMID 41007445, 2025). "The VDR remained in the nucleus after 24 h of treatment in normoglycemic conditions, but this did not occur in hyperglycemia." (PMID 35204769, 2022).
leprosy (18 papers, 2013 to 2026). Leprosy is a chronic infectious disease affecting primarily the skin and peripheral nervous system. "Multiple studies have reported a high prevalence of nutritional deficiencies among leprosy patients, and vitamin D receptor gene expression is reduced in nearly all forms of leprosy compared to healthy controls." (PMID 40621222, 2025). "Some studies have associated polymorphisms of the VDR gene with the risk of leprosy in the Brazilian population and attributed them to the control of the Th1/Th2 cytokine balance, which predicts the clinical evolution of leprosy." (PMID 39166620, 2024). "This association was demonstrated in a study, which showed that VDR gene expression was lower in leprosy patients compared to controls." (PMID 39539349, 2024). "Genotyping analysis identified an association of two functional VDR polymorphisms with leprosy phenotypes, including a missense M1T polymorphism (rs2228570; also known as FokI) of a VDR isoform associated with T1R." (PMID 34746168, 2021). "Early in 1999, the TaqI polymorphism in the 3′ region of the vitamin D receptor (VDR) gene VDR was reported to be associated with leprosy in Indians." (PMID 32373110, 2020). "Haplotypes formed by the BsmI, ApaI, and TaqI polymorphisms of the VDR gene evaluated in all individuals (leprosy per se patients and controls) and MB clinical form (MB patients and controls)." (PMID 31636627, 2019). "Haplotypes formed by the BsmI, ApaI, and TaqI polymorphisms of the VDR gene evaluated in all individuals (leprosy per se patients and controls) and MB clinical form (MB patients and controls) and age cross-classification interaction." (PMID 31636627, 2019). "Single nucleotide polymorphisms in the VDR gene are associated with the different forms of leprosy, as is expression levels of the protein itself." (PMID 30300363, 2018). "It has been shown that The VDR Fok1 ff genotype and Apa1 AA, Aa genotype and haplotype T-f-a, T-F-A were positively associated with leprosy in South-Indian population." (PMID 30481178, 2018). "Genotype and allele frequencies of VDR gene (Taq1, Fok1 and Apa1) polymorphism among leprosy patients and healthy controls." (PMID 30481178, 2018). "In the present study, we investigated the association of VDR gene polymorphism, mRNA gene expression of VDR and the vitamin D levels with leprosy and its reactional states." (PMID 30481178, 2018). "The association of SNPs of VDR gene (Taq1, Fok1 and Apa1), serum level of vitamin D along with VDR mRNA expression with the susceptibility to different phenotypes of leprosy was assessed in this study." (PMID 30481178, 2018). "VDR rs2228570 has been evaluated also in leprosy, an infectious disease caused by another species of Mycobacterium." (PMID 27502545, 2016). "Future studies evaluating the expression of the VDR gene, and the correlation with its SNPs may explain the role of polymorphisms and its influence the immune response in leprosy." (PMID 34143211, 2021). "Further studies analyzing the expression of the VDR gene and the correlation with its SNPs might help to clarify the role of polymorphisms on the immune response in leprosy." (PMID 34143211, 2021). "Furthermore, a silent change in codon 352 of the VDR gene also showed association with leprosy in Malawians." (PMID 32373110, 2020). "Although, the FokI polymorphism has a higher consistency of results related to VDR and leprosy, the BsmI, ApaI, and TaqI polymorphisms, especially the haplotype formed by them, should be further investigated in the immunopathogenesis of leprosy." (PMID 31636627, 2019). "Vitamin D receptor (VDR) gene polymorphism has been found to be associated with leprosy." (PMID 30481178, 2018). "Present study demonstrated that SNP of VDR gene (Fok1 and Taq1) are associated with the leprosy per se and it might be responsible for lower VDR gene expression in leprosy." (PMID 30481178, 2018). "VDR genotypes (Fok1 and Taq1) were found to be associated with leprosy patients." (PMID 30481178, 2018).
leprosy (continued). "A study of the population of Mexico associated the TT genotype in the VDR gene to the lepromatous form of the disease, and also in the population of Calcutta, the tt genotype was associated with Tuberculoid form leprosy, and the TT genotype was associated with Lepromatous form." (PMID 26793196, 2015). "Therefore, considering the role that the active metabolite of VDR exert in the mechanisms of immunity, this study evaluated the association of SNPs (single nucleotide polymorphisms) of the VDR gene (FokI, BsmI, Apal, and TaqI) with the immunopathogenesis and clinical forms of leprosy." (PMID 31636627, 2019). "Although the clinical significance of vitamin D receptor expression remains uncertain, its potential link with disease progression and leprosy reactions has been suggested." (PMID 40621222, 2025). "Futhermore, the expression of the VDR gene among leprosy patients is approx. 5–10% lower when compared with healthy individuals, also reflection in lower levels of 1,25(OH)2D3 in the blood of patients." (PMID 34143211, 2021). "The present study evaluated the association of single nucleotide polymorphisms (SNPs) on the FokI (rs2228570), TaqI (rs731236), ApaI (rs7975232) regions of the vitamin D receptor (VDR) gene with leprosy." (PMID 34143211, 2021). "Low levels of expression, VDR stability and vitamin D3-VDR interaction were related to leprosy and its complications." (PMID 31636627, 2019). "Gene expression of vitamin D receptor was lower in leprosy patients in comparison to healthy controls." (PMID 30481178, 2018). "VDR gene expression was lower in TT/BT and BL/LL groups of leprosy in comparison to that of healthy controls." (PMID 30481178, 2018). "Highest VDR/GAPDH gene expression ratio was observed in T2R cases in comparison to all the phenotypes of leprosy." (PMID 30481178, 2018). "VDR mRNA expression was found to be significantly lower in tuberculoid and lepromatous groups of leprosy." (PMID 30481178, 2018). "Present study was carried out to find out the association of vitamin D receptor (VDR) gene polymorphism, mRNA gene expression of VDR gene and level of vitamin D with leprosy reactions and leprosy patients." (PMID 30481178, 2018). "The polymorphisms in VDR gene (Taq1, Fok1 and Apa1) may affect mRNA stability which in turn affect protein levels and eventually may alter the balance of the production of the Th1 and Th2 related cytokines which is a decisive factor for determining the clinical outcome of leprosy." (PMID 30481178, 2018). "The allele and genotype distribution of each SNP (Taq1, Fok1, Apa1) of VDR gene was in agreement with Hardy-Weinberg equilibrium (p>0.05) in leprosy patients and healthy controls." (PMID 30481178, 2018). "In contrast to the present study earlier it has been reported that VDR mRNA expression was significantly lower in T2R group of leprosy patients in comparison to HC group." (PMID 30481178, 2018). "It has also been reported that mRNA expression for VDR in skin lesions of lepromatous patients is lower in comparison to that with BT/TT leprosy and in T1R." (PMID 30481178, 2018). "Summary of associations between genes of innate immune response MBL2, VDR, NRAMP1, MRC1, and leprosy." (PMID 26793196, 2015). "Although vitamin D levels are not directly associated with leprosy, polymorphisms in the VDR gene have been correlated with disease progression and a higher bacilloscopic index." (PMID 39166620, 2024). "Futhermore, studies involving the detection of VDR gene SNPs in leprosy patients and their healthy contacts in different populations may elucidate aspects of individuals’ immunogenic susceptibility to leprosy and disease severity." (PMID 34143211, 2021). "Therefore, the present study aimed to evaluate the association of SNPs FokI (rs2228570), TaqI (rs731236), ApaI (rs7975232) of the VDR gene with leprosy." (PMID 34143211, 2021).
leprosy (continued). "Genotype frequencies of VDR gene (Taq1, Fok1 and Apa1) polymorphism among Type 1 reaction (T1R), Type 2 reaction patients (T2R) and Non-reaction (NR) leprosy patients." (PMID 30481178, 2018). "Further, an attempt has also been made to investigate the association of VDR gene polymorphism, if any, with leprosy patients with and without reactions." (PMID 30481178, 2018). "Further, low VDR gene expression level in patients might be responsible for impaired immune response in leprosy." (PMID 30481178, 2018). "Although it is reported that the mRNA for the T allele is less stable than the mRNA for the t allele, the association of this allele with the quantitative expression of the VDR mRNA has not yet been confirmed, and we suggest that the tt genotype favors susceptibility to leprosy." (PMID 34143211, 2021). "We have not found any significant association of Apa1 genotype of VDR gene with leprosy." (PMID 30481178, 2018). "We further observed a significantly lower VDR/GAPDH mRNA expression ratio in TT/BT and BL/LL groups of leprosy in comparison to HC group." (PMID 30481178, 2018). "The mean mRNA expression ratios of VDR/GAPDH are identified to be significantly lower in TT/BT and BL/LL group of leprosy in comparison to the HC (TT/BT vs. HC, 0.702 vs. 1.076 and BL/LL vs HC, 0.462 vs 1.076 p < 0.05)." (PMID 30481178, 2018). "Highest mean mRNA expression ratio of VDR/GAPDH was observed in T2R group of leprosy however it is not significant in comparison to HC (T2R vs HC 5.62 vs 1.076, p>0.05) followed by T1R (1.044)." (PMID 30481178, 2018). "Further, VDR gene expression was found to be lower in non-reaction group compared to that of reaction group of leprosy and healthy controls." (PMID 30481178, 2018). "Polymorphisms in innate immune receptor, mannose-binding lectin (MBL), vitamin D receptor (VDR), and nucleotide-binding oligomerization domain (NOD2) genes influence the immune response and the differentiation of the clinical phenotypes of leprosy." (PMID 24498610, 2013). "Further, when we compared mean mRNA expression ratio of VDR/GAPDH between non-reaction (NR) and T1R/T2R groups of leprosy, it was noted that the ratio is not significantly different between the groups (NR vs T1R 0.5894 vs 1.044, p = 0.05; NR vs T2R 0.5894 vs 5.62, p = 0.9529)." (PMID 30481178, 2018).
adenoma (17 papers, 2005 to 2025). A neoplasm arising from the epithelium. "The risk was found to be reduced in individuals with advanced adenoma who had the VDR rs7968585 AA genotype, while an increased risk was observed in those with the VDR rs7968585 GG/GA genotypes." (PMID 40732958, 2025). "This includes with reduced risk of advanced adenoma in individuals with VDR rs7968585 AA genotype and with increased risk of advanced adenoma in individuals with VDR rs7968585 GG/GA genotypes." (PMID 29849001, 2018). "In parathyroid cells, vitamin D inhibits PTH transcription and cell proliferation; a reduction of VDR activity, following the loss of menin, could represent a facilitation for the growth of parathyroid cells and adenoma development." (PMID 32326947, 2020). "More recently, in human studies, it has been shown that functional genetic variants in the vitamin D receptor may also influence any protective response to vitamin D in preventing adenomas, which merits further stratified investigation of the possible effect." (PMID 30103784, 2018). "Two other studies demonstrated mild-to-moderate intensity of VDR staining in adenomas compared to normal tissue samples." (PMID 40186735, 2025). "Although it has been shown that vitamin D supplementation can influence VDR expression, further research is needed to understand how this applies specifically to adenoma or CRC tissue." (PMID 39200386, 2024). "Different epigenetic mechanisms explaining the downregulation of VDR gene expression can also be hypothesized for our remaining ACCs and for some of our adenoma cases with low VDR expression." (PMID 26843863, 2015). "We cannot exclude that low expression of VDR gene in adrenocortical cancers, as well as in some benign adenomas, may rather be due to the effect of hormonal compounds, that is, estrogens, thyroid hormone, and glucocorticoids, which are likewise able to alter VDR mRNA/protein levels." (PMID 26843863, 2015). "Additionally, they found that vitamin D receptor (VDR) polymorphisms were not related to adenoma recurrence and did not modify the associations with vitamin D or calcium." (PMID 27942313, 2011). "The MEN1 gene product “menin” directly interacts with the vitamin D receptor (VDR) and enhances gene transcription, leading to lower VDR expression in adenoma cells." (PMID 38115826, 2023). "Based on this scoring system, the vast majority of tumors were classified as adenomas, showing an average score of 1.4±0.7 for ApcPirc/+VDR+/+ and 1.3±0.5 for ApcPirc/+VDR−/− (P=1)." (PMID 35662320, 2022). "However, most VDR polymorphisms do not result in structural alteration in the VDR protein and are of unknown functional significance and unrelated to adenoma recurrence, and furthermore do not modify the associations with vitamin D or calcium." (PMID 15770204, 2005). "A randomized clinical trial demonstrated that the effectiveness of vitamin D3 supplementation on advanced adenomas, but not on adenoma, varied according to genotype at two VDR SNPs (rs7968585 and rs731236)." (PMID 36776613, 2023).
hypophosphatemia (17 papers, 2010 to 2025). Lower than normal levels of phosphates in the circulating blood. "The causes are broadly divided into failure of vitamin D action and hypophosphatemia; failure of vitamin D action includes the deficiency of vitamin D, abnormal vitamin D metabolism, and abnormalities of the vitamin D receptor." (PMID 27228191, 2016). "1,25(OH)2D/VDR–RXR acts in kidney to induce Klotho (a phosphaturic coreceptor for FGF23) to correct hyperphosphatemia, NPT2a/c to correct hypophosphatemia, and TRPV5 and CaBP28k to enhance calcium reabsorption." (PMID 33553988, 2021).